ZNF283 (zinc finger protein 283)
Description:
May be involved in transcriptional regulation.
Synonyms: HZF19; HZF41
Tractability: PROTAC: UniProt records ubiquitination sites on it; ubiquitination databases record sites on it.
Gene: Protein-coding gene on chromosome 19 (43,827,321 to 43,852,017, forward strand). Ensembl gene ENSG00000167637.
Subcellular location: Nucleus
Subcellular location (Human Protein Atlas): Nucleoplasm
Gene Ontology:
Molecular function: DNA-binding transcription factor activity, RNA polymerase II-specific; RNA polymerase II cis-regulatory region sequence-specific DNA binding
Biological process: regulation of transcription by RNA polymerase II; regulation of DNA-templated transcription
Cellular component: nucleus; nucleoplasm
Genetic constraint (gnomAD): Loss-of-function variants: 4 observed, 6.01 expected, observed/expected ratio (o/e) 0.67, 90% interval 0.33 to 1.49. That is too few expected variants to judge how well the gene tolerates losing a copy. Missense variants: 610 observed, 761.99 expected, observed/expected ratio (o/e) 0.8, 90% interval 0.75 to 0.86. Synonymous variants: 226 observed, 240.84 expected, observed/expected ratio (o/e) 0.94, 90% interval 0.84 to 1.05.
Homologues: Orthologues: chimpanzee ZNF283 (94% identical), macaque ZNF283 (91% identical). Paralogues in human: ZNF331 (45% identical), ZNF546 (43% identical), ZNF540 (40% identical), ZNF571 (38% identical), ZNF841 (37% identical), ZNF836 (37% identical), ZFP14 (35% identical), ZNF461 (35% identical), ZNF573 (35% identical), ZNF30 (34% identical), ZNF528 (34% identical), ZNF33B (34% identical), and 164 more.
Diseases named in the same sentence as ZNF283 in open-access papers:
ZNF283 is named in the same sentence as 5 diseases in open-access papers, as found by Europe PMC text mining. Sharing a sentence is not in itself a finding about the gene and the disease. The quoted sentences say what the papers report.
infection (2 papers, 2018 to 2024). The state of being infected such as from the introduction of a foreign agent such as serum, vaccine, antigenic substance or organism. "ZNF283 depletion significantly increased viral titres and N protein expression in Marc-145 cells throughout the infection process." (PMID 38225617, 2024). "For analysis of the impact of ZNF283 on PRRSV replication, Marc-145 cells were transfected with either HA-tagged ZNF283 plasmids or HA-tagged empty vectors for 24 h before infection with PRRSV for various time periods." (PMID 38225617, 2024). "Both the mRNA and protein expression of ZNF283 significantly increased after infection with high-dose PRRSV." (PMID 38225617, 2024). "We found that upregulation of ZNF283 expression notably decreased the viral titre and the expression of the nucleocapsid (N) protein at 36 h and 48 h post-infection in Marc-145 cells." (PMID 38225617, 2024). "For analysis of the potential involvement of ZNF283 in PRRSV RNA synthesis, Marc-145 cells were transfected with either HA-tagged ZNF283 or an HA-tagged vector for 24 h before infection with PRRSV for 36 h." (PMID 38225617, 2024). "Transcription factors, such as ZNF503, ZNF283, DYM, and OTX1, that control genes involved in antiviral defense may affect downstream targets at later infection stages." (PMID 29997306, 2018).
ZNF283 also shares sentences with these, for which no sentence is quoted: glioma (1 paper); mastitis (1); scrapie (1); viral infection (1).